ELMOD3 (ELMO domain containing 3)
Description:
Acts as a GTPase-activating protein (GAP) for ARL2 with low specific activity.
Synonyms: RBED1; RBM29; FLJ21977; DFNA81; DFNB88; LST3
Tractability: No criterion of Open Targets' tractability assessment is met for any kind of drug.
Gene: Protein-coding gene on chromosome 2 (85,354,394 to 85,391,752, forward strand). Ensembl gene ENSG00000115459.
Subcellular location: Cell projection, stereocilium; Cell projection, kinocilium; Cytoplasm, cytoskeleton
Gene Ontology:
Molecular function: GTPase activator activity; protein binding
Biological process: cilium assembly
Cellular component: cilium; Golgi apparatus; cytoskeleton; kinocilium; stereocilium
Genetic constraint (gnomAD): Loss-of-function variants: 30 observed, 39.87 expected, observed/expected ratio (o/e) 0.75, 90% interval 0.56 to 1.02. The synonymous counts are far from expectation, so gnomAD's model fits this gene poorly and the ratio says little. Missense variants: 345 observed, 408.76 expected, observed/expected ratio (o/e) 0.84, 90% interval 0.77 to 0.92. Synonymous variants: 126 observed, 166.49 expected, observed/expected ratio (o/e) 0.76, 90% interval 0.65 to 0.88.
Gene-disease validity (ClinGen):
ClinGen rates the evidence that ELMOD3 causes each of these diseases.
nonsyndromic genetic hearing loss (autosomal dominant; autosomal recessive): Limited. A disease characterized by hearing loss that is not part of a larger syndrome.
Homologues: Orthologues: macaque ELMOD3 (91% identical), rabbit ELMOD3 (87% identical), chimpanzee ELMOD3 (85% identical), pig ELMOD3 (85% identical), guinea pig ELMOD3 (81% identical), mouse Elmod3 (80% identical), rat Elmod3 (79% identical), dog ELMOD3 (75% identical), tropical clawed frog elmod3 (48% identical), zebrafish elmod3 (44% identical), Caenorhabditis elegans elmd-1 (17% identical). Paralogues in human: ELMO3 (18% identical), ELMO1 (17% identical), ELMOD1 (16% identical), ELMO2 (16% identical), ELMOD2 (14% identical).
Diseases named in the same sentence as ELMOD3 in open-access papers:
ELMOD3 is named in the same sentence as 11 diseases in open-access papers, as found by Europe PMC text mining. Sharing a sentence is not in itself a finding about the gene and the disease. The quoted sentences say what the papers report.
deafness (5 papers, 2013 to 2023). An inherited or acquired condition characterized by the complete loss of the ability to hear from one or both ears. "ELMO domain-containing 3 (ELMOD3) was identified as a new deafness gene implicated in causing HL in humans." (PMID 37210555, 2023). "We identified one homozygous transition mutation, c.794T>C (p.Leu265Ser), in ELMOD3 on chromosome 2p11.3 that segregated with DFNB88-linked deafness." (PMID 24039609, 2013). "Exome sequencing coupled with homozygosity mapping was used to identify a transition mutation (c.794T>C; p.Leu265Ser) in ELMOD3 at the DFNB88 locus that is associated with nonsyndromic deafness in a large Pakistani family, PKDF468." (PMID 24039609, 2013). "The current work found a series of DEGs related to sensory epithelial development and cytoskeleton organization through functional enrichment and PPI network analysis, including ATOH1, VIM, PRPH and NEFL, which may be involved in the pathogenesis of ELMOD3 causing deafness." (PMID 37708136, 2023). "Based on the reported autosomal recessive inheritance in a consanguineous Pakistani family affected with non-syndromic deafness (DFNB88; OMIM #615429), hearing loss was attributed to the homozygous deletion of ELMOD3 in this patient." (PMID 38137045, 2023). "Among them were four genes associated with deafness [grainyhead like transcription factor 2 (GRHL2), BCL2 like 11 (BCL2L11), ELMO domain containing 3 (ELMOD3), usherin (USH2A)]." (PMID 32835229, 2020). "Furthermore, previous studies on the mechanism of ELMOD3 induced deafness mainly focused on abnormal stereocilia morphology." (PMID 37708136, 2023).
hearing loss (4 papers, 2013 to 2025). "In the current work, we successfully reprogrammed B lymphocytes from a hearing loss patient with ELMOD3 c.512A>G mutation into iPSCs, based on the Yamanaka method." (PMID 37708136, 2023). "Our current work provided a new tool for studying how disruption of ELMOD3 mechanistically drives hearing loss." (PMID 37708136, 2023). "The ELMOD3 gene is implicated in causing autosomal recessive/dominant non-syndromic hearing loss in humans." (PMID 37708136, 2023). "The iPSCs cell model established in this study is not only an effective tool to study how disruption of ELMOD3 mechanistically drives hearing loss, but also provides a potential tool to carry out gene therapy research in the future." (PMID 37708136, 2023). "In-depth analysis of high throughput RNA sequencing data between the patient-specific iPSCs and the corrected iPSCs, we attempt to know more about how disruption of ELMOD3 mechanistically drives hearing loss." (PMID 37708136, 2023). "Two pathogenic ELMOD3 gene mutations have been found, leading to either autosomal recessive pre-speech hearing loss or autosomal dominant progressive hearing loss." (PMID 37708136, 2023). "Exome enrichment followed by massive parallel sequencing revealed a c.794T>C transition mutation in ELMOD3 that segregated with DFNB88-associated hearing loss in a large Pakistani family." (PMID 24039609, 2013). "Similarly, a patient-derived iPSC line carrying the ELMOD3 c.512A > G mutation has been generated to study ELMOD3, which is implicated in causing autosomal recessive/dominant non-syndromic hearing loss." (PMID 41227304, 2025). "Therefore, in this study we chose to generate patient-specific human iPSCs carrying c.512A>G mutation, which could be used as an iPSC-based disease model for pursuing how disruption of ELMOD3 causes hearing loss." (PMID 37708136, 2023). "Also, if inner-ear-like tissue could be derived from these iPSC lines in the next step, coupled with transcriptome and proteome profiling could be conducted at that stage, we could further extend our understanding of the molecular etiology of ELMOD3 causing hearing loss." (PMID 37708136, 2023). "Recently, a homozygous deletion affecting the last three exons of ELMOD3, the entire CAPG gene, and the first non-coding exon of SH2D6 has been identified in a Tunisian ASD proband with ID and hearing impairment." (PMID 30736458, 2019).
autism spectrum disorder (2 papers, 2023). A spectrum of developmental disorders that includes autism, and Asperger syndrome. "A copy number variation analysis suggests that microdeletion of SH2D6 may be responsible for the generation of chimeric transcripts by ELMOD3 and SH2D6 fusions, which may be involved in autism spectrum disorder (ASD) phenotypes along with other variants." (PMID 37554505, 2023).
autosomal dominant non-syndromic deafness (2 papers, 2023). "In our previous study, a heterozygous ELMOD3 c.512A>G (p.His171Arg) variant was identified as a causative variant in a five-generation Chinese family affected by late-onset and progressive autosomal dominant non-syndromic hearing loss (ADNSHL)." (PMID 37708136, 2023).
autism (1 paper, 2019). Persistent deficits in social interaction and communication and interaction as well as a markedly restricted repertoire of activity and interest as well as repetitive patterns of behavior. "In order to assess the relevance and test the frequency of ELMOD3-CAPG-SH2D6 in ASD susceptibility in autism and control populations, we exploited large-cohort whole-genome CNV data already available." (PMID 30736458, 2019).
breast carcinoma (1 paper, 2024). "ELMOD3 has been reported in past breast cancer studies, which neither disagree with nor invalidate our findings." (PMID 39409999, 2024).
lung adenocarcinoma (1 paper, 2025). A carcinoma that arises from the lung and is characterized by the presence of malignant glandular epithelial cells. "In conclusion, we hereby report, for the first time, a case of lung adenocarcinoma harboring a novel ELMOD3-ALK and EML4-ALK double-ALK fusion." (PMID 40297141, 2025). "Herein, we first report a lung adenocarcinoma patient with the coexistence of a novel subfamily 3 of ELMOD (ELMOD3)-ALK, EML4-ALK double fusion that is sensitive to alectinib target therapy." (PMID 40297141, 2025). "This is the first report of one lung adenocarcinoma patient with a novel ELMOD3-ALK, EML4-ALK double-ALK fusion." (PMID 40297141, 2025). "This is the first case presenting a rare coexistence of a novel ALK double fusion, namely, ELMOD3-ALK and EML4-ALK, in a patient with lung adenocarcinoma who demonstrated favorable sensitivity to alectinib." (PMID 40297141, 2025). "In this study, we report, for the first time, a novel ELMOD3-ALK and EML4-ALK double fusion identified by next-generation sequencing (NGS) in a patient with lung adenocarcinoma." (PMID 40297141, 2025).
cancer (1 paper, 2025). A tumor composed of atypical neoplastic, often pleomorphic cells that invade other tissues. "However, no studies have reported an association between the ELMOD3 gene and cancer." (PMID 40297141, 2025).
tumour (1 paper, 2023). "With an immunoprecipitation assay with proteins expressed in cultured tumour cells, we investigated molecular mechanism, by which ELMOD3 regulates lumen formation." (PMID 36918025, 2023).
ELMOD3 also shares sentences with these, for which no sentence is quoted: Hearing impairment (2 papers); Rett syndrome (1).